FOXP1 (forkhead box P1)
Diseases named in the same sentence as FOXP1 in open-access papers (continued):
Sharing a sentence is not in itself a finding about the gene and the disease.
ovarian carcinoma (continued). "Levels of FoxP1 expression were shown to be elevated in TILs as compared to non-tumor-associated T cells in ovarian cancer patients." (PMID 36829573, 2023). "As we found that FOXP1 upregulation in ovarian cancer tumorsphere was significantly prevented by EGCG, FOXP1 may constitute an attractive target for the development of therapeutics to eliminate CSC in ovarian cancer." (PMID 37189618, 2023). "Similarly, miR‐374b‐5p targets FOXP1 and exerts a protective role in non–small‐cell lung cancer and ovarian cancer." (PMID 34890108, 2022). "In addition, a recent study has shown that miR-29c-3p downregulates ATG14 by inducing the expression of FOXP1 to inhibit autophagy and promote cisplatin resistance in ovarian cancer cells." (PMID 33898430, 2021). "Additionally, a recent study demonstrated that FOXP1 can function as an oncogene and a CSCs driver gene in epithelial ovarian cancer cells." (PMID 33898430, 2021). "FOXP1 drives ovarian cancer stem cell‐like characteristics by functioning as an oncogene." (PMID 33006432, 2020). "To determine whether FOXP1 is involved in the progression of aggressiveness in ovarian cancer, we tested the effect of FOXP1 expression on proliferation and migration of ovarian cancer cells." (PMID 26654944, 2016). "Targeting FOXP1 may provide a novel therapeutic opportunity for developing a relapse-free treatment for ovarian cancer patients." (PMID 26654944, 2016). "Furthermore, FOXP1 still serves as an oncogene through promoting the cancer stem cell-like characteristics of ovarian cancer cells." (PMID 27457567, 2016). "In addition, the inhibition of FOXP1 in ovarian cancer decreased CSC characteristics." (PMID 40169859, 2025). "In addition, FOXP1 knockdown significantly inhibited in vivo growth of ovarian cancer cells." (PMID 26654944, 2016). "In addition, FOXP1 is reported to be an estrogen-inducible and androgen-inducible transcription factor —a factor that may be correlated with its oncogenic function in hormone-sensitive breast cancer, ovarian cancer, and prostate cancer." (PMID 39623140, 2025). "Other transcripts that were upregulated during ovarian cancer spheroids formation include DACH1, the Discoidin domain receptor (DDR1), the winged helix transcription factor Forkhead box P1 (FOXP1), and MUC1." (PMID 37189618, 2023). "In ovarian cancer, XIST was shown to regulate the miR-506-3p/FOXP1 axis, in turn regulating autophagy and carboplatin resistance." (PMID 36869839, 2023). "By activating autophagy and targeting the miR-506-3p/FOXP1 axis, the long non-coding RNA XIST was responsible for promoting a carboplatin resistance in ovarian cancer." (PMID 36766800, 2023). "Taken together, we showed correlation of FOXP1 expression with the promotion of CSC characteristics, such as the enhancement of spheroid formation, proliferation, and migration, in ovarian cancer cells." (PMID 26654944, 2016). "In the current study, we showed FOXP1 up-regulated transcription activity of ABCG2, OCT4, NANOG, and SOX2 in A2780 ovarian cancer cells." (PMID 26654944, 2016). "For example, in ovarian cancer cells, ABCB1 expression may be regulated by transcription factors such as forkhead box protein P1 (FOXP1), or through hormonal modulation by estrogen and progesterone." (PMID 41303640, 2025). "To determine whether FOXP1 is involved in the regulation of CSC-like characteristics, we tested the effect of FOXP1 knockdown or overexpression on spheroid formation in A2780 and SKOV3 ovarian cancer cells." (PMID 26654944, 2016). "Though broader spectrum of CSCs may need to be tested to evaluate how common FOXP1 to core CSC transcription network, FOXP1 up-regulates expression of CSC-related core transcription factors, including ABCG2, OCT4, NANOG, and SOX2, in ovarian cancer cells." (PMID 26654944, 2016).
ovarian carcinoma (continued). "FOXP1 upregulates the transcriptional activities of four key stemness factors, ATP Binding Cassette Subfamily G Member2 (ABCG2), octamer-binding transcription factor 4 (OCT4), nanog homeobox (NANOG) and SOX2, to promote CSCs-like features in ovarian cancer cells." (PMID 33898430, 2021). "Recently, in analysis of tissue samples from ovarian cancer patients, Lin's group reported negative correlation of nuclear expression of FOXP1 with increasing tumor grade and poor prognosis, suggesting that FOXP1 may function as a tumor suppressor." (PMID 26654944, 2016). "However, the function of FOXP1 in ovarian cancer has not been clear." (PMID 26654944, 2016). "However, in ovarian cancer, the precise role of FOXP1 in CSCs has not been clearly characterized." (PMID 26654944, 2016).
prostate carcinoma (26 papers, 2014 to 2025). A carcinoma that arises from epithelial cells of the prostate gland. "In intrahepatic cholangiocarcinoma and prostate cancer, overexpression of FOXP1 was associated with tumor suppression." (PMID 40169859, 2025). "Overall, this study reveals that loss of Foxp1 increases cell proliferation, whereas loss of Foxa1 induces epithelial plasticity in prostate cancer." (PMID 36139541, 2022). "FOXP1 deletion is involved in prostate cancer and neuroblastoma proliferation and is associated with prognosis." (PMID 35122700, 2022). "FOXP1 has the highest number of somatic point mutations in prostate cancer, including H515R/Y and the adjacent L519del in the forkhead domain, which are also seen in other cancers." (PMID 29057879, 2017). "Combined loss of PTEN and the 3p14 deletion gene FOXP1 is therefore prognostic for prostate cancer recurrence, highlighting the functional cooperativity of these alterations." (PMID 29057879, 2017). "On the other hand, loss of FOXP1 expression was reported in renal cell carcinoma, prostate cancer, lung cancer, and endometrial cancer, with an association with the worse outcome." (PMID 26654944, 2016). "Similarly, FOXP1 is associated with HIFs and androgen receptor (AR) in prostate cancer and downregulates AR-induced transcriptional activities and histone modifications in enhancer regions." (PMID 32552834, 2020). "FOXP1 knockdown was shown to promote tumor growth and invasion in lung adenocarcinoma, while FOXP1 overexpression can suppress cell migration and proliferation in rectal and prostate cancer cells." (PMID 38279090, 2024). "Our results reveal that Foxp1 is a tumor suppressor in prostate cancer progression by controlling proliferation and genes regulated by the androgen receptor." (PMID 36139541, 2022). "The family of Forkhead box (FOX) transcription factors are often altered in prostate cancer with especially high mutation burden in FOXA1 and FOXP1." (PMID 36139541, 2022). "From the PCA analysis results, we found that the roles of FOXA1, NFYA, and FOXP1 in regulating stemness genes in normal prostate samples were changed by comparing those in prostate cancer samples." (PMID 33985534, 2021). "FOXP1 has been described as a target of chromosomal translocations and amplifications in B-cell lymphomas and prostate cancer." (PMID 29464086, 2018). "In sum, both DNA and RNA analysis of prostate tissue confirmed deletion of the entire Foxp1-Shq1 locus similar to that seen in human prostate cancer." (PMID 29057879, 2017). "In addition to accelerating cancer progression, deletion of the Foxp1-Shq1 locus with Pten loss results in changes in signaling, such as mTORC1 activation and restored nuclear hormone receptor activity, that are mirrored in human prostate cancers with comparable genotypes." (PMID 29057879, 2017). "Specifically, combined FOXP1 and PTEN loss (defined as copy number or expression loss) is associated with prostate cancer recurrence in multiple cohorts." (PMID 29057879, 2017). "Similar results have recently been published for prostate cancer and non-small cell lung cancer, in which an inverse correlation of FOXP1 expression with increased malignancy grade and reduced patient survival was observed." (PMID 25406647, 2014). "Forkhead box (FOX) transcription factor family members FOXA2 and FOXP1 were also among the proteins with binding sites most strongly associated with negative TMRs and have both previously been implicated in prostate cancer." (PMID 41036619, 2025). "Knockdown of FOXP1 in LNCaP prostate cancer cells resulted in increased migration in vitro." (PMID 38374116, 2024). "FOXP1 is a prostate cancer suppressor that regulates androgen receptor and FOXA165." (PMID 36138066, 2022). "The Coremine website finds approximately 18, 250, and 4 articles for FOXP1, RELA, and KDM2B related to prostate cancer." (PMID 37403016, 2023).
prostate carcinoma (continued). "While prostate cancer recurrence was not statistically significantly associated with combined genomic loss of PTEN and FOXP1-SHQ1, inclusion of Foxp1 expression loss revealed a prognostic association with recurrence." (PMID 29057879, 2017). "A multigenic locus at 3p13-14, spanning FOXP1 to SHQ1, is commonly deleted in prostate cancer and lost broadly in a range of cancers but has unknown significance to oncogenesis or prognosis." (PMID 29057879, 2017). "Foxp1-Shq1f/f;Ptenf/f mice showed accelerated oncogenesis with highly anaplastic histopathology compared to Ptenf/f mice, while Foxp1-Shq1f/f mice showed no obvious prostate cancer phenotype." (PMID 29057879, 2017). "Androgen-dependent gene expression is also decreased in human prostate cancers with PTEN loss alone (compared to tumors without PTEN loss) but is partially restored in tumors with combined PTEN and FOXP1 loss." (PMID 29057879, 2017). "Both the CSS for prostate cancer and the FFS for DLBCL were derived from only one dataset and neither showed significant associations with the decreased FOXP1 protein expression (HR = 2.51, 95%CI: 0.92–6.83, p = 0.071; HR = 0.71, 95%CI: 0.26–1.94, p = 0.504, respectively)." (PMID 27457567, 2016). "Furthermore, analysis of FOXP1 and TMPRSS2 expression in a human prostate cancer data set revealed a negative correlation." (PMID 36139541, 2022).
lung carcinoma (25 papers, 2013 to 2025). "The FOXP1 gene, which is involved in repressing pro-apoptotic genes, has been reported to be silenced in kidney and colon cancers, while its high expression has been associated with better prognosis in breast and lung cancers, aligning with these findings." (PMID 38893160, 2024). "Further studies showed that circ FOXP1 can increase the expression of SLC7A11 by directly sponging miR-520a-5p in lung cancer cells to promote lung cancer tumor growth." (PMID 37005430, 2023). "More studies have found that FOXP1 and FOXP2 are expressed in lung tissue, and FOXP1 plays an antitumour role in the development of lung cancer." (PMID 35281860, 2022). "A study has examined the role of FOXP1 (Forkhead box protein P1) in lung cancer which suggested its essentiality in preventing the development of lung adenocarcinoma via suppression of chemokine signaling pathways." (PMID 35885958, 2022). "LEF1-AS1 contributes to proliferation and invasion by regulating the miR-544a/FOXP1 axis in lung cancer." (PMID 34922523, 2021). "In particular, hsa-mir-19a affects the survival at the first stage, which regulates biological molecules such as grape seed procyanidin, MTUS1, c-Met, and FOXP1 to affect lung cancer." (PMID 32428028, 2020). "Further, our combined prognosis showed that the combined high expression of SP5, FOXP1, ROBO1, DPP4, CDYL2, and STAMBPL1 is associated to patients’ better clinical prognosis of patients with lung cancer." (PMID 32552834, 2020). "Here, we show that LEF1-AS1 promotes proliferation and invasion in lung cancer by regulating the miR-544a/ FOXP1 axis." (PMID 30734202, 2019). "Genetic aberrations of Foxp1 loci at chromosome 3p14.1 have been reported in many cancers including lung cancer and neuroblastoma." (PMID 26367773, 2015). "For instance, the rs9309336 locus may affect the binding site of the transcription factor FOXP1 and regulate the expression of the CHD1L gene, thereby influencing the risk of lung cancer." (PMID 41049290, 2025). "FOXP1 activates Wnt/β‐catenin in lung cancer to promote EMT." (PMID 32239639, 2020). "Furthermore, overexpression of FOXP1 inhibits proliferation and invasion in U251 glioma cells, while knockdown of FOXP1 promotes the development of lung carcinoma." (PMID 31815635, 2019). "Therefore, the LEF1-AS1/miR-544a/FOXP1 axis is an important contributor to lung cancer progression." (PMID 30734202, 2019). "Fundamentally, the LEF1-AS1/miR-544a/FOXP1 axis is an important contributor to lung cancer progression and that disrupting these signaling pathways could provide a novel mechanism for treating lung cancer." (PMID 30734202, 2019). "These apCAFs subsequently recruit FOXP1+ regulatory T cells through PD-L2-RGMB interactions, contributing to neoadjuvant immunotherapy resistance in early-stage lung cancer." (PMID 40358847, 2025). "Some studies have found that circ FOXP1 was significantly overexpressed in the serum of NSCLC patients, and the down-regulation of circ FOXP1 can inhibit the proliferation of lung cancer cells." (PMID 37005430, 2023). "In lung cancer, ectopic expression of miR-1 reduced the protein levels of MET, Pim-1, FoxP1, and HDAC4 to influence the survival of cancer cells and oncogenic properties." (PMID 28537886, 2017). "LPP, FOXP1 and NFE2L2 have previously been reported in lung cancer and we have reported the rest of the genes for the first time in lung adenocarcinoma." (PMID 23874428, 2013). "It was reported that the treatment with HDAC as an inhibitor of lung cancer cells could induce the expression of repressed miR-1 by the downregulation of oncogenes such as MET, PIM1, FOXP1, and HDAC4." (PMID 37569812, 2023). "Our results revealed that miR-19a downregulates the target genes FOXP1, TP53INP1, TNFAIP3, and TUSC2 and that these genes might play important roles in the tumorigenesis of lung cancer; however, the invasion inhibition potency was found to differ among the four genes." (PMID 26367773, 2015).
B-cell lymphomas (23 papers, 2007 to 2025). "FOXP1 protein expression has been detected in 40-60% of DLBCL cases, and strong expression of FOXP1 has been associated with poorer prognosis in patients with some B-cell lymphomas." (PMID 24887414, 2014). "Altogether, our data support the important role of FOXP1-associated rearrangements in development and progression of B-cell lymphoma." (PMID 24416450, 2014). "The transcription factor FOXP1 is implicated in the pathogenesis of B-cell lymphomas through chromosomal translocations involving either immunoglobulin heavy chain (IGH) locus or non-IG sequences." (PMID 24416450, 2014). "FOXP1 has previously been linked to B-cell lymphoma while ZNF831 is overall poorly studied." (PMID 39878215, 2025). "In addition, miR-34a repression was described to cause high-grade transformation of B-cell lymphoma by altering FOXP1 (Forkhead Box P1) expression." (PMID 30201877, 2018). "In the current study we have demonstrated that immune suppression is a critical mechanism by which tumor cell expression of Foxp1 promotes in vivo growth in the A20 B-cell lymphoma model." (PMID 32309216, 2020). "In BL, FOXP1 levels are comparable to GC-B cells, but lower than the level in other B-cell lymphomas." (PMID 33261009, 2020). "High expression of FOXP1 in B cell lymphoma or hepatocellular carcinoma was shown to play a role as an oncogene, showing correlation with the worse outcome." (PMID 26654944, 2016). "High expression of FOXP1 was reported in a variety of B-cell lymphomas, in which FOXP1 plays an oncogenic role." (PMID 26654944, 2016). "In contrast, high expression of FOXP1 was shown to correlate with poor outcome in certain types of B cell lymphomas." (PMID 25406647, 2014). "However, B-cell lymphomas overexpress FOXP1, and individuals who have increased FOXP1 expression typically have a substandard prognosis." (PMID 37626655, 2023). "To date, a number of biomarkers with a diagnostic value for each B-cell lymphoma subtype have been determined: BCL2, BCL6, CD10, CD21, and STMN1 in FL; D1 and SOX11 in MCL; FOXP1 and MUM1 in ABC-DLBCL; CD10, BCL2, BCL6, LMO2, and GCET1 in GC-DLBCL; and CD30, CD15, EBV, BOB1, OCT2, and CD79a in HL." (PMID 37894763, 2023). "However, another report showed that, although short FOXP1 isoform is preferentially expressed in B-cell lymphomas, overexpressed full-length FOXP1 has a similar oncogenic activity." (PMID 36268015, 2022). "This contrasts with the oncogenic role of Foxp1 in B-cell lymphoma." (PMID 32951006, 2020). "However, FOXP1 is overexpressed in B-cell lymphomas, and patients with higher FOXP1 expression tend to have a worse prognosis." (PMID 30360388, 2018). "Interestingly, 45% of FOXP1+ extranodal marginal zone B-cell lymphomas also have trisomy 3, and FOXP1 expression correlates with poor survival." (PMID 19662221, 2007). "Interestingly, FOXP1 can be also detected in marginal zone B-cell lymphomas." (PMID 19662221, 2007). "Distinction between different types of B-cell lymphoma, pseudo-B-cell lymphoma, and secondary cutaneous B-cell lymphoma is made using Bcl-2, Bcl-6, CD10, MUM-1, and FOXP1." (PMID 29147306, 2012). "Surprisingly, this was not the case for B-cell lymphomas, which suggests different role of FOXP1 in these cell types." (PMID 36268015, 2022). "We collected four B-cell lymphoma cases with the FISH proven 3p13/FOXP1 chromosomal aberrations not involving IG loci (further referred to as index cases)." (PMID 24416450, 2014).